RN7SKP245 (RN7SK pseudogene 245)
Gene: Miscellaneous RNA gene on chromosome 6 (131,820,334 to 131,820,653, forward strand). Ensembl gene ENSG00000200895.
Homologues: Orthologues: chimpanzee 7SK (87% identical), guinea pig 7SK (58% identical). Paralogues in human: 7SK (76% identical), RN7SKP255 (73% identical), RN7SKP180 (73% identical), RN7SKP187 (73% identical), RN7SKP269 (73% identical), RN7SKP30 (73% identical), RN7SKP120 (72% identical), RN7SKP133 (72% identical), RN7SKP176 (72% identical), RN7SKP257 (72% identical), RN7SKP44 (72% identical), RN7SKP214 (72% identical), and 283 more.